MMP10 (matrix metallopeptidase 10)
Diseases named in the same sentence as MMP10 in open-access papers (continued):
Sharing a sentence is not in itself a finding about the gene and the disease.
chronic kidney disease (8 papers, 2020 to 2025). Impairment of the renal function secondary to chronic kidney damage persisting for three or more months. "We and others have demonstrated that serum concentration of MMP-10 is elevated in chronic kidney disease (CKD) associated with vascular complications." (PMID 31913319, 2020). "Recent studies revealed that MMP‐10 aggravated podocyte dysfunction and proteinuria by disrupting glomerular filtration integrity via degrading ZO‐1 in chronic kidney disease." (PMID 37382248, 2023). "An early increase in MMP-10 and TIMP-1 was observed and a further progressive elevation was found as DKD progressed to end-stage renal disease." (PMID 31913319, 2020). "While MMP-10 is reno-protective in acute kidney injury (AKI) by promoting HG-EGF-mediated injury repair and regeneration, it also contributes to the pathogenesis of chronic kidney diseases (CKD)." (PMID 35216251, 2022). "The expression of MMP-10 is induced in acute kidney injury (AKI) and chronic kidney disease (CKD), as well as in renal cell carcinoma (RCC)." (PMID 35216251, 2022).
diabetic nephropathy (8 papers, 2015 to 2025). "The results showed significant enrichment of the type I diabetes pathway in both the high expression groups of KLK1 and MMP10, suggesting their association with the progression of diabetic nephropathy." (PMID 39606015, 2024). "Among type 1 diabetic patients, those with high serum MMP-10 levels exhibit a higher risk of developing diabetic nephropathy." (PMID 35216251, 2022). "In fact, glucose-induced mesangial matrix remodelling has been suggested as a mechanism leading to nephropathy, and thus MMP-10 has been suggested as a potential drug target to slow down diabetic nephropathy and retinopathy." (PMID 31805809, 2020). "Moreover, serum MMP‐10 levels progressively increased in patients with diabetic nephropathy, as the severity of the disease increased." (PMID 39740102, 2025). "MMP-10 protein was increased in renal tubules of CKD, including IgA nephropathy (IgAN), diabetic nephropathy (DN) and lupus nephritis (LN)." (PMID 40382334, 2025). "In addition, MMP-10 knockout (streptozotocin (STZ)-induced) diabetic mice showed lower renal mesangial cell expansion and lower renal macrophage influx compared to wildtype diabetic mice, suggesting that MMP-10 may be involved in the onset of diabetic nephropathy." (PMID 25848912, 2015).
head and neck cancer (8 papers, 2011 to 2024). A primary or metastatic malignant neoplasm affecting the head and neck. "Among the SASP factors we investigated in the current study, in addition to MMP1 and MMP3, overexpression of MMP10 has been reported to promote invasion, metastasis in head and neck cancer, and tongue cancer." (PMID 39756915, 2024). "Expression levels of MMP10, MMP19, MMP24, and MMP25 were associated with prognosis in TCGA cohort of head and neck cancer by Kaplan-Meier analysis." (PMID 32850314, 2020). "Expression levels of MMP10, MMP19, MMP24, and MMP25, which were associated with prognosis in head and neck cancer, were identified using Kaplan–Meier method and log-rank test." (PMID 32850314, 2020).
Nephropathy (8 papers, 2015 to 2025). A nonspecific term referring to disease or damage of the kidneys. "For example, high levels of serum MMP-9 and a high MMP-9-to-TIMP ratio have been related to retinopathy, and high levels of plasma MMP-10 have been associated with nephropathy and proliferative retinopathy." (PMID 25848912, 2015). "In particular, Mmp7, Mmp10, and Mmp12 were highlighted for their differential expression between strains and their potential role in influencing the severity of kidney damage." (PMID 38674390, 2024). "MMP-10 remodels matrix, and its degradation products promote mesangium expansion, which leads to nephropathy, so MMP-10 has been suggested as a reliable drug target to attenuate the progression of retinopathy and DN." (PMID 36013381, 2022). "In this review, we summarize our current understanding of the role of MMP-10 in kidney diseases and discuss the potential mechanisms of its actions." (PMID 35216251, 2022). "As Wnt/β-catenin is activated in all kinds of AKI and CKD examined, these findings suggest a widespread induction of MMP-10 in various kidney disorders." (PMID 35216251, 2022). "A detailed understanding of the molecular and cellular events involved in MMP-10 action is prerequisite for designing rational strategies for the therapeutic management of kidney diseases." (PMID 35216251, 2022). "In conclusion, we demonstrate for the first time an association between MMP-10 and TIMP-1 and the different stages of renal disease, as well as glomerular overexpression of Mmp10 in T2DM, which is prevented by blocking RAS." (PMID 31913319, 2020). "Similarly, marked induction of MMP-10 expression was also evident in animal model of folic acid-induced nephropathy (FAN)." (PMID 40382334, 2025). "We also found, using the Olink proteomic platform, that TNF-α and TMAO enhanced the secretion of additional inflammatory-and growth mediators associated with kidney disease; VEGFA, GDNF, CDCP1, OPG, uPA, AXIN1, MMP-1, MMP-10, PD-L1, HGF, Flt3L, 4E-BP1, CD40, CASP-8, ADA, TNFRSF9, TWEAK44–61." (PMID 38643262, 2024). "In one large study of 269 type 1 diabetes patients and 269 non-diabetic controls, plasma MMP-10 was associated with nephropathy and proliferative retinopathy." (PMID 25848912, 2015). "Our study demonstrates that circulating MMP-10 is increased in T2DM, together with its inhibitor TIMP-1, starting at the earliest stages of DKD, and their concentration increases with the severity of kidney disease." (PMID 31913319, 2020). "The role of MMP-10 in kidney disease has not been extensively studied." (PMID 31913319, 2020). "Interestingly, the findings of the present study are relevant for identifying an up-regulation of MMP-10 and TIMP-1 in T2DM, even before overt kidney disease is noted, and opens the door for future studies aiming at elucidating the mechanistic role of this MMP and its inhibitor on DKD." (PMID 31913319, 2020).
oral cancer (8 papers, 2011 to 2024). "It has been demonstrated that MMP10 may serve as a diagnostic and prognostic marker in patients with gastric cancer and those with oral cancer, suggesting an important role of MMP10 in cancer progression." (PMID 22200787, 2012). "The expression levels of MMP7, MMP13 and MMP10 were validated to be significantly upregulated in oral cancer compared with normal samples according to the data mining of published profiles in Oncomine." (PMID 31996191, 2020). "Among those differentially expressed, MMP10, a potential biomarker for prediction of nodal metastases in oral cancer (unpublished data), was found to be significantly higher in the Fusobacterium-high subgroup, suggesting a potential association between the Fusobacterium load and nodal metastases." (PMID 35252868, 2022). "Moreover, other group showed that MMP-10 is a potential oral cancer marker." (PMID 21998657, 2011). "After analyzing the data related to oral cancer using the Cancer Genome Atlas, Oncomine, and Kaplan-Meier mapper, the MMP3 and MMP10 are identified as highly altered hub genes of oral cancer." (PMID 38302910, 2024).
Sepsis (8 papers, 2009 to 2024). Sepsis is defined as life-threatening organ dysfunction caused by a dysregulated host response to infection. "One previous study linked elevated serum levels of MMP-10 to sepsis in human patients." (PMID 28045063, 2017). "Higher MMP-2, MMP-8, MMP-9, MMP-10, TIMP-1 and MMP-10/TIMP-1 were seen in severe sepsis compared to controls." (PMID 34043679, 2021). "An association was found between MMP-9, MMP-10, TIMP-1, and MMP-9/TIMP-1 ratios and parameters of sepsis severity, assessed by the SOFA score, the APACHE-II score, lactic acid, platelet count, and markers of coagulopathy." (PMID 19799791, 2009). "Sepsis patients had higher levels of MMP-10 and TIMP-1, higher MMP-10/TIMP-1 ratios, and lower MMP-9/TIMP-1 ratios than did healthy controls (P < 0.001)." (PMID 19799791, 2009). "In addition, circulating levels of MMP10 are significantly higher in patients with sepsis, suggesting an important role for this proteinase during infection." (PMID 23691065, 2013). "Taken together, these results indicate that an alteration in the MMP-9/TIMP-1 ratio and MMP-10 levels may be of great pathophysiologic significance in sepsis patients." (PMID 19799791, 2009). "• MMP-9/TIMP-1 ratio and MMP-10 levels may be of great pathophysiologic significance in terms of severity and mortality in sepsis patients." (PMID 19799791, 2009). "In addition, we report for the first time that sepsis patients have higher levels of MMP-10 than do controls." (PMID 19799791, 2009). "Therefore, besides the already known higher mortality rate in sepsis patients with increased lactic acid levels and SOFA score, our results suggest that alterations in the MMP-9/TIMP-1 ratio and MMP-10 levels are associated with the severity of sepsis." (PMID 19799791, 2009). "The association of the MMP-1 (-1607 1G/2G) SNP and sepsis might be due to linkage disequilibrium with the MMP-13 SNP because the MMP-13 and MMP-1 genes are both located in the same cluster of the chromosome 11q22-23 along with the MMP-3, MMP-7, MMP-8, MMP-10, MMP-12, and MMP-20 genes." (PMID 24833564, 2014). "The objective of this study was to determine the predictive value of MMP-9, MMP-10, and TIMP-1 on clinical severity and mortality in a large series of patients with severe sepsis." (PMID 19799791, 2009). "Serum levels of MMP-9, MMP-10, TIMP-1, tumor necrosis factor (TNF)-alpha, and interleukin (IL)-10 were measured in patients with severe sepsis at the time of diagnosis and in healthy controls." (PMID 19799791, 2009). "At week 1, the only protein with significant differences in plasma between infants who developed sepsis and infants who did not was MMP10, with higher levels in infants with sepsis." (PMID 38001236, 2024). "Thus, the objective of this study was to determine the influence of the circulating levels of MMP-9, MMP-10, and TIMP-1 on the severity and mortality of patients with sepsis in a large cohort." (PMID 19799791, 2009). "Although higher levels of MMP-9 and tissue inhibitor of matrix metalloproteinases-1 (TIMP-1) have been found in small series of patients with sepsis, MMP-10 levels have not been studied in this setting." (PMID 19799791, 2009). "Moreover, higher levels of TIMP-1 (P < 0.001), reduced MMP-9 (P = 0.037), and a nonsignificant increase of MMP-10 were found in nonsurviving as compared with surviving sepsis patients." (PMID 19799791, 2009).
esophageal cancer (7 papers, 2014 to 2023). A primary or metastatic malignant neoplasm involving the esophagus. "Recently, MMP10 was found to be essential for pro-MMP activation; a high expression of MMP10 was observed in tumors epithelial cells, such as transitional cell cancer of the bladder, gastric cancer, skin cancer esophageal cancer, and NSCLC." (PMID 36908704, 2023). "Recently, MMP10 was shown to play a significant role in pro-MMPs activation; it is expressed at high levels in epithelial tumors like bladder transitional cell cancer, gastric cancer, esophageal cancer, NSCLC, and skin cancer." (PMID 36908704, 2023). "However, the importance of MMP-10 on metastasis in oesophageal cancer is less reported in the literature." (PMID 33126685, 2020). "Through the integration of data information, it was found that the variable shear factor QKI was closely related to the epithelial mesenchymal transformation (EMT) of oesophageal cancer, and QKI might promote the EMT process by activating the expression of IL-11, MFAP2, MMP10 and MMP1." (PMID 37428781, 2023).
head and neck squamous cell carcinoma (7 papers, 2015 to 2023). A squamous cell carcinoma that arises from any of the following anatomic sites: lip and oral cavity, nasal cavity, paranasal sinuses, pharynx, larynx, and salivary glands. "Elevated levels of MMP-10 protein have been observed in tumors, including non-small cell lung cancer, head and neck squamous cell carcinoma, bladder transitional cell carcinoma, epithelial skin cancer, renal cell carcinoma, and colon adenocarcinoma." (PMID 26415518, 2015). "Survival analysis suggests high expression of MMP10 or AXL was significantly (p < 0.05) associated with poor overall survival of head and neck squamous cell carcinoma (HNSCC) patients, but not just tongue cancer patients, which could be because there were fewer tongue cancer patients." (PMID 36650344, 2023).
idiopathic pulmonary fibrosis (7 papers, 2015 to 2025). Idiopathic pulmonary fibrosis (IPF) is a nonneoplastic pulmonary disease that is characterized by the formation of scar tissue within the lungs in the absence of any known cause. "A previous study evaluating the degree of pulmonary fibrosis induced by ultrafine amorphous silica also demonstrated that the expression of MMP-10 was associated with pulmonary fibrosis." (PMID 26415518, 2015). "Additionally, previous studies have implicated MMP10 as a novel biomarker for idiopathic pulmonary fibrosis, reflecting both disease severity and prognosis in patients with idiopathic pulmonary fibrosis." (PMID 33066398, 2020). "The same has been described in the lung, where serum levels of MMP10 in patients with idiopathic pulmonary fibrosis are low in contrast to the abundant expression of MMP10 in lung tissue." (PMID 35884862, 2022). "MMP-10 reportedly localized to fibrotic regions and alveolar macrophages in cerium oxide-treated lungs and silica-induced pulmonary fibrosis." (PMID 26415518, 2015). "Importantly, our discoveries further demonstrated the role of these MMPs and TIMPs in lung fibrosis, including MMP-10 as a new contributor, and revealed, for the first time, variation in their levels depending on the type of ILD." (PMID 39979794, 2025). "Fibrosis-related genes include Col1a1, Acta2, Fn1, and Tgfb1 gene, and senescence-related genes composed of Cdkn2a, Tnf, Serpine1, Ccl2, Mmp10, and Mmp12 gene, all of which reflected the intensity of lung fibrosis and senescence events in lung tissue and pulmonary fibroblasts." (PMID 35662697, 2022). "Taken together, MMP-10 may be involved in the pathogenesis of pulmonary fibrosis, as with other MMPs, such as MMP-1 and -7." (PMID 26415518, 2015). "Therefore, pulmonary fibrosis may be induced by TGF-β through several pathways, including MMP-10." (PMID 26415518, 2015).
non-small cell lung carcinoma (7 papers, 2011 to 2023). A group of at least three distinct histological types of lung cancer, including non-small cell squamous cell carcinoma, adenocarcinoma, and large cell carcinoma. "In non-small cell lung cancers, MMP10 plays a pertinent role in tumor initiation, and it maintains the characteristics of CSCs." (PMID 23626764, 2013). "Our findings are supported by a recent paper showing that PKCι–Par6α–Rac1 signaling axis promoted anchorage-independent growth and invasion of non small cell lung carcinoma (NSCLC) cells through induction of MMP-10 expression." (PMID 21998657, 2011). "Additionally, MMP-10 (stromelysin-2) has been overexpressed in various cancers including gastric, bladder, renal, esophageal, skin, and non-small cell lung cancer." (PMID 36505884, 2022).
renal cell carcinoma (7 papers, 2012 to 2024). "MMP-10 expression is also increased in renal cell carcinoma (RCC) and its levels are associated with poor prognosis and decreased 5-years survival of RCC patients." (PMID 33436543, 2021). "In response to diverse insults, MMP-10 can be induced in various cells, including the renal tubular epithelium, glomerular podocytes, juxtaglomerular apparatus, as well as renal cell carcinoma." (PMID 35216251, 2022). "Therefore, MMP-10 is regarded as a potential therapeutic target to inhibit the invasion and the metastases of renal cell carcinoma." (PMID 36231910, 2022). "Moreover, it was observed that MMP-10 is present in the cytoplasm of renal cell carcinoma cells." (PMID 36231910, 2022). "In patients with renal cell carcinoma (RCC), immunohistochemical staining reveals that induction of MMP-10 is primarily detected in tubular cancer cell cytoplasm." (PMID 35216251, 2022).
type 1 diabetes (7 papers, 2015 to 2024). "Nevertheless, the study indicated an association among MMP-3 and MMP-10, and macrovascular and microvascular complications in patients with type 1 diabetes." (PMID 33371324, 2020). "In the high MMP10 expression subgroup, pathways significantly enriched included those associated with allograft rejection, systemic lupus erythematosus, type I diabetes, mucin-type O-glycan biosynthesis, and graft-versus-host disease (see relevant figures for details)." (PMID 39606015, 2024). "Previous data about the association of high MMP-10 levels with microvascular complications in diabetes type 1 in clinical and experimental studies could explain the association found in ICH patients." (PMID 32587306, 2020). "Plasma levels of MMP10 are associated with albuminuria in patients with type 1 diabetes." (PMID 33224151, 2020). "In this study with type 1 diabetic patients, plasma MMP-2, MMP-3, MMP-10 and TIMP-1 levels are associated with macro- and microvascular complications and these associations were largely independent of LGI and ED." (PMID 25848912, 2015). "It is noteworthy that, regardless of whether in the high expression group of KLK1 or MMP10, the type I diabetes pathway was significantly enriched." (PMID 39606015, 2024). "An association between high serum levels of MMP-10 and a greater risk of DKD has been previously shown in type 1 diabetes (T1DM), and the absence of Mmp10 in a murine model protected against renal macrophage infiltration and mesangial expansion." (PMID 31913319, 2020).
endometriosis (6 papers, 2008 to 2025). The growth of functional endometrial tissue in anatomic sites outside the uterine body. "Analysis showed only weak expression of MMP10 in endometriosis (Fig. 2C1), with both glands and stroma showing lower expression than adjacent tissue (ΔTIS -0.24, p=0.197 and -1.13, p<0.001)." (PMID 39373851, 2024). "These cells showed changes in growth profiles, were characterized by high expression of matrix metalloproteinases (MMP) MMP3 and MMP10, and may have a role in endometriosis etiology." (PMID 36746607, 2023). "A similar fibroblast signature characterized by MMP3 and MMP10 was observed in menstrual fluid of patients with endometriosis, suggesting these altered fibroblasts may be maintained during menstruation and may represent a possible non‐invasive diagnosis signature." (PMID 36746607, 2023). "MMP10, PAEP and IL1B revealed low expression in endometriosis, while showing a positive staining in positive control tissue, and are therefore not considered potential for further research." (PMID 39373851, 2024). "In order to clarify the role of metalloproteases and their inhibitors in endometriosis development, MMP2, MMP3, MMP10, TIMP1, and TIMP2 expression was measured in healthy and eutopic endometrium, in OMA and DIE lesions." (PMID 32325785, 2020). "Several MMPs such as MMP1, MMP2, MMP 3, MMP10, MMP 11, and MMP 14 are identified as endometriosis-specific genes." (PMID 19055724, 2008).